TLR7 (toll like receptor 7)
Diseases named in the same sentence as TLR7 in open-access papers (continued):
Sharing a sentence is not in itself a finding about the gene and the disease.
multiple sclerosis (12 papers, 2012 to 2026). A progressive autoimmune disorder affecting the central nervous system resulting in demyelination. "Interestingly, an endogenous ligand of TLR7, U11snRNA, was detected in the sera of 2D2TgDcir -/- mice and the patients of multiple sclerosis, indicating excessive DC activation by TLR7-mediated signaling in 2D2TgDcir -/- mice and patients with a neuronal autoimmune disease." (PMID 42256301, 2026). "In PBMCs obtained from patients with multiple sclerosis, IFN-β upregulated the mRNA of MyD88, TLR3, and TLR7, whereas TLR9 mRNA expression was suppressed." (PMID 30103522, 2018). "In vivo treatment with IFN-β induces TLR7 upregulation and TLR9 down modulation in PBMCs of patients with multiple sclerosis." (PMID 29052537, 2017). "In multiple sclerosis, the role of IFN-β in the activation of TLR7 in pDCs was demonstrated." (PMID 30103522, 2018). "In addition, loxoribine (an agonist of TLR7) increased the IFN-α production in PBMCs pretreated with IFN-β, suggesting that the activation of TLR7 induces the production of type I IFN in multiple sclerosis." (PMID 30103522, 2018).
Sjögren’s syndrome (12 papers, 2014 to 2025). "Therefore, the aim of this study was to investigate phenotype and functional properties of immature and TLR7/8 stimulated monocyte-derived DC (moDC) of patients with primary Sjögren’s syndrome (pSS) and compare them to healthy controls." (PMID 25113744, 2014). "This increased risk is thought to be mediated by immune-related genes on the X chromosome, such as TLR7 and CXorf21, that escape X inactivation, leading to overexpression and heightened immune activation, which helps explain the strong female predominance observed in Sjögren’s syndrome." (PMID 40429780, 2025). "In humans, TLR7 and TLR9 are upregulated in patients with Sjogren's syndrome." (PMID 24904837, 2014).
AIDS (11 papers, 2011 to 2024). A syndrome resulting from the acquired deficiency of cellular immunity caused by the human immunodeficiency virus (HIV). "In this study, we analyzed polymorphisms in the X-linked TLR7 gene in the rhesus macaque model of AIDS." (PMID 22022401, 2011). "Upon targeted TLR7 re-sequencing in 36 rhesus macaques of Indian origin, we detected 12 polymorphisms and subsequently investigated their possible association with AIDS-free survival and viremia in SIV-infected animals." (PMID 22022401, 2011). "Endocytosis of HIV-1 activates pDCs via interactions of TLR7 and viral RNA, and TLR7 persistent activation also contributes to chronic activation of the immune system which is closely related with AIDS progress." (PMID 33193416, 2020). "We demonstrate that HIV disease progression is influenced by TLR7/8 expression and signaling in monocytes, offering additional targets in the pursuit of treatments and cures for AIDS." (PMID 22243920, 2012). "Next, we analyzed the influence of the TLR7 SNPs upon AIDS-free survival and viral load in 72 immunized-infected male monkeys." (PMID 22022401, 2011). "On the other hand, TLR7-triggered pathways appear to be directly involved in immune pathogenesis leading to AIDS." (PMID 22022401, 2011). "Because HIV activates TLR7 pathway, the linkage between TLR7 and EBV might play a role in the development of AIDS-associated lymphomas." (PMID 22952664, 2012). "Our results highlight the dual role of TLR7 in immunodeficiency virus infection and vaccination and imply that it may be important to control human AIDS vaccine trials, not only for MHC genotype, but also for TLR7 genotype." (PMID 22022401, 2011). "Assuming that the c.13A and c.-17T,c.13G variants are associated with enhanced TLR7 expression, the data suggest that efficient triggering of TLR7 may improve AIDS vaccine efficacy while attenuating the action of TLR7 may decelerate disease progression." (PMID 22022401, 2011). "On the other hand, activation of PRR pathways such as TLR2 and TLR4 may lead to inflammation, promoting HIV replication and accelerating the progression of AIDS, while TLR7 and TLR8 may increase the expression of NF-κB, inhibiting HIV replication and delaying the progression of AIDS in ECs/LTNPs." (PMID 35211115, 2022). "Furthermore, the polymorphism of TLR7 and TLR9 SNPs are associated with HIV susceptibility, and some mutations may delay the development of AIDS in ECs or LTNPs." (PMID 35211115, 2022). "Taken together, expression of TLR7 and TLR8 in monocytes was correlated with AIDS disease progression and appeared to decrease as with advancing severity of disease from SPs to AIDS." (PMID 22243920, 2012). "As TLR7 is an important player to trigger the IFN-γ production, which exerts a direct antiviral effect through the inhibition of viral replication, it is also involved in the progression of HIV infection to AIDS." (PMID 32565728, 2020). "Indeed, we found that TLR7 and TLR8 expression levels in monocytes declined as a function of the severity of HIV infection (i.e. slow progression to chronic HIV infection to AIDS)." (PMID 22243920, 2012). "TLR7 expression was decreased significantly at each subsequent stage of HIV infection, while TLR8 expression decreased significantly from baseline levels only at the AIDS stage." (PMID 22243920, 2012). "Both programs predicted that the Q11L (rs179008) polymorphism, which has been reported to influence viral load and time to AIDS in humans, does not influence the secondary structure of the human TLR7 signal peptide-coding RNA." (PMID 22022401, 2011). "In HIV infection, TLR7-triggered IFN-α production exerts a direct antiviral effect through the inhibition of viral replication, but may also be involved in immune pathogenesis leading to AIDS." (PMID 22022401, 2011).
allergic asthma (11 papers, 2010 to 2025). A asthma with a basis in a pathological type I hypersensitivity reaction. "In contrast to these studies, RANTES was shown to aid in the resolution of allergic asthma when stimulated with recombinant formulations or by TLR7/8 stimulation with R848." (PMID 40149931, 2025). "Previous work found that the toll-like receptor 7 agonist R-848 suppresses allergic asthma when transcutaneously administered in a mouse model of birch pollen allergy." (PMID 32120968, 2020). "This study in patients with allergic asthma demonstrated that intranasal administration of the TLR7 agonist AZD8848 attenuated the average post-allergen LAR fall in FEV1 and prevented an increase in AHR following allergen challenge 1 week after the last dose." (PMID 31856838, 2019). "TLR7 agonists have potential as a new treatment option for allergic asthma by reducing responsiveness to allergens." (PMID 31856838, 2019). "TLR7 agonists have potential as a new treatment option for allergic asthma through the stimulation of Th1/Th0 effector cells, thereby attenuating allergen-specific Th2 cells." (PMID 31856838, 2019). "In allergic asthma, TLR7 activated pDC produce less IL-6, IFN-α, and TNF than pDC from healthy people." (PMID 29118754, 2017). "In this study, we used an established mouse model of acute allergic airway inflammation, relevant to human allergic asthma, to address the role of TLR7 in the resolution of inflammation and identify specific SPM networks involved." (PMID 23584892, 2013). "This strengthens the rationale for the application of TLR7/8 agonists for the treatment of allergic asthma and respiratory allergies in general, and supports their development for other diseases driven by non-resolving inflammation." (PMID 23584892, 2013). "We tested the effect of agonists of TLR2 (P40 protein of Klebsiella pneumoniae and the Pam3Cys lipopeptide), TLR3 (double-stranded RNAs Poly(I∶C)), TLR4 (LPS and lipid A) and TLR7 (R848) on experimental allergic asthma and autoimmune diabetes in the NOD mouse." (PMID 20628601, 2010). "The TLR7/8 agonist R848, known as resiquimod, is a member of the imidazoquinoline family and is an anti-inflammatory therapeutic agent that can be used to alleviate allergic asthma and chronic asthma via direct injection in mouse models." (PMID 40025520, 2025). "In patients with allergic asthma, TLR7 agonists could potentially reduce allergen responsiveness by stimulating Type 1 interferon responses to down-regulate the dominant Th2 responses." (PMID 31856838, 2019). "As several TLR7 or TLR7/8 agonists are under clinical development for the treatment of various diseases including respiratory allergies, their efficacy in clinical trials of allergic asthma exacerbations are eagerly awaited." (PMID 23584892, 2013). "We decided to determine whether the TLR7 response was involved in the pathology of allergic asthma." (PMID 33093516, 2020). "Others have, using various animal models, demonstrated beneficial effects of TLR7 agonists in allergic asthma and a recent clinical trial has shown encouraging results, suggesting that TLR7 agonists might be a novel alternative for treatment of allergic rhinitis." (PMID 22857391, 2012). "Several research findings also revealed that TLR7 regulates RV1b-induced type I and type III interferon signaling pathways in allergic asthma." (PMID 38341589, 2024). "Allergic asthma was induced with OVA-alum, and the therapeutic effects of anti-TLR7 mAb and anti-TLR9 mAb were determined." (PMID 33093516, 2020).
Allergy (11 papers, 2012 to 2025). An allergy is an immune response or reaction to substances that are usually not harmful. "Two TLRs implicated in allergy are TLR7 and TLR8, as studies have found variants in TLR7 and 8 genes contribute to genetic risk for atopic disease." (PMID 27042301, 2016). "Among next-generation adjuvants, TLR agonists, particularly TLR7/8, are promising in allergy immunotherapy due to their ability to promote both humoral and Th1 responses." (PMID 40951841, 2025). "Genetic polymorphisms in immune regulatory genes, such as IL10 and Toll-like receptor 7 (TLR7), have been implicated in modulating the Th1/Th2 balance and influencing susceptibility to allergic diseases." (PMID 41465112, 2025). "Preclinical studies utilizing TLR7 ligation revealed promising results in the treatment of cancer, allergy, and infectious diseases." (PMID 26770023, 2015). "If chronic HCV infection indeed promotes a tolerogenic immune state via IL-10 and TLR7 pathways, therapeutic strategies aimed at enhancing such regulatory circuits could be explored in allergic disease." (PMID 41465112, 2025). "However, until now, no data have been available describing the application of the TLR7 activator CL264 as adjuvant for the treatment of allergic diseases." (PMID 29204451, 2017). "Interestingly, in mice that constitutively overexpress IL-5 (IL-5Tg/Tg mice) TLR7 expression was significantly reduced and was associated with accumulation of eosinophils in the airways in the absence of allergy." (PMID 26108570, 2015). "In several experimental allergy models, such conjugates, for example, incorporating TLR5-, TLR7/8-, and TLR9-ligands, have been described to have beneficial immune-modulating properties by promoting Th1- and appropriate regulatory responses." (PMID 27340679, 2016). "TLR7 and TLR9 ligands have shown promise in clinical trials as immunotherapeutics for the treatment of cancer, allergy, and infectious diseases." (PMID 26770023, 2015). "Previous studies investigating the effects of adjuvant : allergen fusion proteins, including TLR5-, TLR7-, and TLR9-ligands, on the modulation of allergen-specific immune responses demonstrated the potential for such conjugate vaccines to improve allergy treatment." (PMID 27340679, 2016). "TLR7 expression in the lungs was suppressed by allergic inflammation and by interleukin (IL)-5-induced eosinophilia in the absence of allergy." (PMID 26108570, 2015).
gastric cancer (11 papers, 2018 to 2025). A primary or metastatic malignant neoplasm involving the stomach. "We speculate that TLR7 may be a high-risk factor due to its low expression in gastric cancer." (PMID 34367971, 2021). "TLR7 was lowly expressed in rectum cancer tissue and highly expressed in stomach cancer tissue at protein levels." (PMID 37362864, 2023). "Conjugation of TLR7 agonist to gastric cancer antigen MG7-Ag exerts antitumor effects and have synergistic antitumor effects with 5-fluorouracil via T cell activation and MDSCs inhibition." (PMID 36476317, 2022). "A study in 30 patients with gastric cancer showed that the mRNA and protein expression levels of TLR7 were significantly downregulated in gastric cancer tissues." (PMID 36476317, 2022). "Increased TLR7 expression promotes the production of proinflammatory cytokines and inhibits the growth of gastric cancer cells." (PMID 34367971, 2021). "Overall, either used alone or used as an adjuvant, TLR7 agonist has been shown as an anti-tumor agent in immunotherapy of gastric cancer currently." (PMID 33469538, 2020). "Imiquimod can induce the expression of TLR7 protein, promote inflammatory cytokines secreting, and inhibited cell proliferation in one of the human gastric cancer cell lines." (PMID 33469538, 2020). "In that study, TLR7 expression was low in gastric cancer cells compared to levels in adjacent healthy tissue." (PMID 31467388, 2019). "Yet, administering imiquimod (a TLR7 agonist) to gastric cancer cells results in a reduced proliferation." (PMID 31467388, 2019). "Unfortunately, the number of patients in this subgroup was too small to draw definitive conclusions; our results, however, encourage further study of TLR7 expression in early-stage gastric cancer." (PMID 31467388, 2019). "The administration of a TLR7 agonist, imiquimod, increases the expression of TLR7 in gastric cancer cells and reduces their viability." (PMID 31467388, 2019). "Gastric cancer vaccines were synthesized by the covalent attachment of our TLR7 agonist with the gastric cancer antigen MG7-Ag tetra-epitope, leading to T7 − ML (linear tetra-epitope) and T7 − MB (branched tetra-epitope)." (PMID 29739434, 2018). "In this study, we constructed novel gastric cancer vaccines using collaborative applications of our TLR7 agonist (T7) and the MG7-Ag tetra-epitope." (PMID 29739434, 2018). "We have constructed a series of vaccines by covalently attaching a small-molecule TLR7 agonist to a gastric cancer antigen, leading to immunogenicity stimulation and tumor inhibition when introduced to animal models." (PMID 29739434, 2018). "Previous studies have found that TLR7 expression is reduced in stomach cancer." (PMID 34367971, 2021). "Therefore, in this study, we aimed to explore the tissue expression of TLR1, TLR2, TLR4, TLR5, TLR7, and TLR9 as potential prognostic biomarkers in gastric cancer patients, and to examine their associations with several clinicopathological variables." (PMID 31467388, 2019). "TLR7 was previously thought to reduce the viability of gastric cancer cells." (PMID 31467388, 2019). "In addition, we found that a high expression of TLR1, TLR2, TLR4, TLR5, TLR7, and TLR9 associated with an intestinal-type gastric cancer and with a high expression of all other TLRs." (PMID 31467388, 2019). "However, our results did not associate TLR7 polymorphism with clinical features, survival, or oral cancer susceptibility, in line with previous findings in lung, or gastric cancer." (PMID 38850110, 2024). "Ma et.al developed a bi-functional vector containing a Bcl-2-silencing shRNA and a TLR7-stimulating ssRNA, which promoted apoptosis and inhibited cell growth in MFC cells (a mouse gastric cancer cell line)." (PMID 33469538, 2020). "In conclusion, we certified the application of TLR7 agonists and the MAP structure in the design of gastric cancer vaccines, with T7 − MB providing benefits to tumor-bearing mice via CTLs and ADCC-mediating antibodies recognizing MG7-Ag." (PMID 29739434, 2018).
gastric cancer (continued). "We have reported the importance of covalently attaching the TLR7 agonist and the MG7-Ag epitope to designing gastric cancer vaccines." (PMID 29739434, 2018). "Recently, the tissue expressions of TLR1, TLR2, TLR4, TLR5, TLR7 and TLR9 as potential prognostic biomarkers in gastric cancer were reported, showing a positive correlation between each other and a high expression of each studied TLR in tumors with an intestinal-type histology." (PMID 40362298, 2025). "In a small subgroup of stage I disease, none of the patients with a high TLR7 expression died from gastric cancer." (PMID 31467388, 2019). "Amongst patients with a high TLR7 expression and stage I disease, no deaths due to gastric cancer were recorded during our follow-up period (HR 0.03; 95% CI 0.01–97.7; p = 0.392)." (PMID 31467388, 2019). "Thus, we aimed to evaluate the tissue expressions of TLR1, TLR2, TLR4, TLR5, TLR7, and TLR9 as potential prognostic biomarkers in gastric cancer." (PMID 31467388, 2019). "Interestingly, we recorded no gastric cancer–related deaths among stage I patients with a high TLR7 expression." (PMID 31467388, 2019). "We first aimed to evaluate the role of TLR7 in NSCLC cells, paying particular attention to its impact on tumor angiogenic potential in order to verify whether its role is similar to that of FPR1 in gastric cancer (GC)." (PMID 33578955, 2021). "In addition to TLR5, TLR1, TLR2, TLR4, TLR7, and TLR9 were also expressed in gastric cancer tissues, yet their expression levels did not function as prognostic biomarkers across the entire patient cohort." (PMID 31467388, 2019).
hepatitis C (11 papers, 2011 to 2023). "TLR7 agonists have effectively lower viremia in hepatitis C patients, presumably due to the induction of endogenous IFN production." (PMID 27135246, 2016). "Human T-cells purified from HIV and from Hepatitis C patients were also shown to express TLR7 and/or TLR9." (PMID 21253574, 2011). "Due to X skewing might affect the interpretation of data in female, we disregard TLR7 SNP heterozygous females from analysis and got a significant difference in homozygous TLR7 IVS2-151genotypes among controls and hepatitis C female patients (p = 0.021; OR = 8.55,95% CI = 0.99 to 73.4)." (PMID 22022576, 2011).
Immunodeficiency (11 papers, 2015 to 2025). Failure of the immune system to protect the body adequately from infection, due to the absence or insufficiency of some component process or substance. "Further research is needed to better understand TLR7 variants and its implications in immunodeficiency and immune dysregulation." (PMID 40423910, 2025). "X-linked TLR7 deficiency has been identified as a novel immunodeficiency with an increased susceptibility to severe or critical COVID-19 infection and TLR7 has been established as a critical mediator of IFN-I immunity against the virus." (PMID 36204639, 2022). "Interestingly, despite these immune deficiencies, TLR7 KO mice exhibited higher expression of proinflammatory markers, as well as elevated levels of TLRs and RLRs, in the nasal tissue compared to WT mice." (PMID 40442368, 2025). "Among these, agonists of toll-like receptor 7 (TLR7) appear promising therapeutics that may be able to overcome the HBV-associated immunodeficiencies present in patients." (PMID 35677037, 2022). "TLR7-ATM deficiency may cause two distinct immunodeficiency phenotypes." (PMID 37521843, 2022). "X-linked TLR7 deficiency has been identified as the first novel immunodeficiency with an isolated, increased susceptibility to severe or critical SARS-CoV-2 infection and has established TLR7 as a critical mediator of IFN-I immunity against SARS-CoV-2." (PMID 35986347, 2022). "At present, it is not clear whether the TLR7 loss of function results in a pleiotropic immunodeficiency or is dominated by a B cell intrinsic effect of TLR7." (PMID 36648888, 2023). "Toll-like receptor 7 (TLR7) is mainly expressed on DCs, monocytes, T lymphocytes, and B lymphocytes and has regulatory roles in immunodeficiency diseases and immune regulation." (PMID 37160878, 2023).